TRAPPC5 (trafficking protein particle complex subunit 5)
Description:
May play a role in vesicular transport from endoplasmic reticulum to Golgi.
Synonyms: MGC52424; TRS31
Tractability: PROTAC: ubiquitination databases record sites on it; its protein half-life has been measured.
Gene: Protein-coding gene on chromosome 19 (7,680,833 to 7,687,703, forward strand). Ensembl gene ENSG00000181029.
Subcellular location: Golgi apparatus, cis-Golgi network; Endoplasmic reticulum
Subcellular location (Human Protein Atlas): Vesicles
Pathways (Reactome):
Vesicle-mediated transport: COPII-mediated vesicle transport; RAB GEFs exchange GTP for GDP on RABs
Gene Ontology:
Molecular function: protein binding
Biological process: COPII vesicle coating; endoplasmic reticulum to Golgi vesicle-mediated transport; vesicle coating; Golgi vesicle transport
Cellular component: TRAPP complex; cytoplasm; cytosol; TRAPPI protein complex; TRAPPII protein complex; TRAPPIII protein complex; endoplasmic reticulum; Golgi apparatus
Genetic constraint (gnomAD): Loss-of-function variants: 5 observed, 6.72 expected, observed/expected ratio (o/e) 0.74, 90% interval 0.39 to 1.53. That is too few expected variants to judge how well the gene tolerates losing a copy. Missense variants: 243 observed, 262.55 expected, observed/expected ratio (o/e) 0.93, 90% interval 0.83 to 1.03. Synonymous variants: 146 observed, 123.92 expected, observed/expected ratio (o/e) 1.18, 90% interval 1.03 to 1.35.
Homologues: Orthologues: macaque TRAPPC5 (99% identical), pig TRAPPC5 (99% identical), guinea pig TRAPPC5 (99% identical), mouse Trappc5 (99% identical), rat Trappc5 (99% identical), zebrafish trappc5 (79% identical), tropical clawed frog trappc5 (77% identical), rabbit TRAPPC5 (64% identical), Drosophila melanogaster Trs31 (63% identical), dog TRAPPC5 (63% identical), Caenorhabditis elegans trpp-5 (51% identical).
Diseases named in the same sentence as TRAPPC5 in open-access papers:
TRAPPC5 is named in the same sentence as 4 diseases in open-access papers, as found by Europe PMC text mining. Sharing a sentence is not in itself a finding about the gene and the disease. The quoted sentences say what the papers report.
Sepsis (2 papers, 2020 to 2021). Sepsis is defined as life-threatening organ dysfunction caused by a dysregulated host response to infection. "Previous studies have suggested that lncRNAs may be potential biomarkers for prognosis of sepsis, such as lncRNAs MALAT1, NEAT1, RP11-1220 K2.2.1–7, ANXA3–2, TRAPPC5–1, and ZNF638–1, which have been introduced in introduction." (PMID 34483898, 2021). "The qPCR results were similar to those acquired from microarray, suggest that the 4 lncRNAs (lncRNA lnc-RP11-1220 K2.2.1–7, lncRNA lnc-ANXA3–2, lncRNA lnc-TRAPPC5–1, lncRNA lnc-ZNF638–1) are significantly highly expressed in septic children and could be novel biomarkers for pediatric sepsis." (PMID 32151258, 2020).
colon cancer (1 paper, 2021). "The proteomic analysis of colon cancer indicated that the protein levels of TRAPPC3, TRAPPC4, TRAPPC5, and TRAPPC8 significantly correlated with that of PD-L116." (PMID 34518538, 2021).
hepatocellular carcinoma (1 paper, 2024). A malignant tumor that arises from hepatocytes. "One report identified upregulation of TRAPPC5 in hepatocellular carcinoma (HCC) subsequent to knockout of CCT4, a key component of HCC glycolytic metabolism." (PMID 39769094, 2024).
tumor (1 paper, 2008). "FatiGO+ analysis showed that tumor libraries had significantly more expressed genes related to "cell organization and biogenesis" (GO:0016043), KRT7, PDIA3, PPGB and TRAPPC5 (p = 0.005); and "ligase activity" (GO:0016874), UBE2S and MTHFD1 (p = 0.028) than normal libraries." (PMID 18302799, 2008).